KCNMA1 (potassium calcium-activated channel subfamily M alpha 1)
Diseases named in the same sentence as KCNMA1 in open-access papers (continued):
Sharing a sentence is not in itself a finding about the gene and the disease.
channelopathy (continued). "Since the prior review in 2019, the cohort of patients identified with KCNMA1-linked channelopathy has nearly doubled, and the number of studies addressing the functional effects of KCNMA1 variants on BK channel activity has expanded." (PMID 34224328, 2021). "There are several important additional caveats to translating KCNMA1 mutation effects assessed from in vitro patch-clamp experiments into even a basic understanding of the molecular role of patient variants in KCNMA1-linked channelopathy." (PMID 34224328, 2021). "KCNMA1-linked channelopathy typically presents with either epileptic seizures or movement dysfunction, or both, often without remarkable brain imaging or EEG." (PMID 34224328, 2021). "KCNMA1-linked channelopathy is a rare disorder, with the available allele frequencies estimated to be 1:100,000 for KCNMA1 mutations." (PMID 34224328, 2021). "At present, the disorder “KCNMA1-linked channelopathy” is so named to reflect that it is solely defined by a neurological diagnosis in conjunction with a mutation in the KCNMA1 gene." (PMID 34224328, 2021). "While rare mutations underlie the described cases of KCNMA1-linked channelopathy, single nucleotide polymorphisms (SNPs) comprise the majority of the sequence variation between individuals." (PMID 34224328, 2021). "This review expands the phenotypic spectrum for KCNMA1-linked channelopathy and presents an updated summary of the clinical picture observed among patients." (PMID 34224328, 2021). "Together, this review provides additional evidence exploring the genetic and biochemical basis for KCNMA1-linked channelopathy and summarizes the clinical repository of patient symptoms across multiple types of KCNMA1 gene variants." (PMID 34224328, 2021). "In this review, we summarize 37 KCNMA1 alleles from 69 patients currently defining the channelopathy and assess key diagnostic and clinical hallmarks." (PMID 34224328, 2021). "This larger dataset offers the opportunity to update the phenotypic range and variability of KCNMA1-linked channelopathy, and to begin to evaluate potential associations between KCNMA1 variants, BK channel activity, and patient symptoms." (PMID 34224328, 2021). "This review includes SNPs to further probe the landscape of KCNMA1 variants linked to disease and to evaluate the overlap with potential KCNMA1-linked channelopathy pathogenesis." (PMID 34224328, 2021). "Summarizing the symptomatic range identified among patients with KCNMA1-linked channelopathy therefore provides a basic set of descriptors for the spectrum of diagnoses following identification of a KCNMA1 mutation." (PMID 34224328, 2021). "In this study, to test the hypothesis that human patient mutations in the KCNMA1 gene would cause a disruption in the circadian rhythm, we assessed the circadian behavior for three KCNMA1 channelopathy mouse models." (PMID 37728576, 2023). "In addition, we compile a table of mutations implicated in KCNMA1-linked channelopathies, with their known functional consequences and the predicted ∆V1/2." (PMID 37713443, 2023). "Moreover, a rare disease called KCNMA1-linked channelopathy, is also characterized by seizures and abnormal movements associated with the clinical detection of a KCNMA1 variant." (PMID 36834817, 2023). "KCNMA1‐linked channelopathy is a rare movement disorder first reported in 2005." (PMID 35141357, 2022). "Neurologic abnormalities associated with KCNMA1 mutations or variants of unknown significance (VUS) are described as KCNMA1‐linked channelopathy." (PMID 35141357, 2022). "Following the identification of a mutation in the KCNMA1 gene, it remains challenging to sort through the etiology of the various symptoms associated with the channelopathy, which may be either episodic or present persistently." (PMID 34224328, 2021).
channelopathy (continued). "However, apart from qualitative movement disorder findings, prior studies uncovered few distinctions between GOF and LOF variants with respect to core KCNMA1-linked channelopathy patient phenotypes." (PMID 34224328, 2021). "However, cataplectic events, especially in children, can have a broad phenotype that overlaps with the paroxysmal dyskinesias seen in KCNMA1-linked channelopathy." (PMID 34224328, 2021). "Future studies expanding and refining the genotypic and phenotypic findings presented here, in tandem with a more comprehensive, stratified analysis of the biochemical basis of KCNMA1-linked channelopathy, may illuminate a path toward improved mechanistic understanding and therapeutics." (PMID 34224328, 2021). "Additionally, it cannot be ascertained at this time whether these phenotypes are primary effects of KCNMA1 mutations or secondary to channelopathy-provoked seizures." (PMID 34224328, 2021). "Genetic mutations in KCNA1, CACNA1A, CACNB4, SLC1A3, SCN8A, KCNMA1, and ATP1A3 genes that encode ion channels lend support to the channelopathy theory." (PMID 37008993, 2023). "Although some KCNMA1 channelopathy patients anecdotally report sleep disturbances, it is difficult to disentangle an antecedent circadian defect from other neurological-associated symptoms in this new disorder." (PMID 37728576, 2023). "Uncovering the basis for patient sleep disturbances remains an interesting new dimension within the neurological landscape of KCNMA1 channelopathy." (PMID 37728576, 2023). "Genotype-phenotype relationships are important for understanding KCNMA1 channelopathy disease mechanisms as well as potential therapeutics." (PMID 35819138, 2022). "The underlying channelopathy pathway accounted for 46.7% (7/15) of the monogenic variants, including ion channel genes (SCN1A, KCTD7, KCNC1, CACNA1A, KCNMA1) and ligand-gated ion channel genes (GABRA1, GABRG2)." (PMID 36034301, 2022). "One of the most recognizable symptoms in KCNMA1 channelopathy is a distinctive type of dyskinesia manifesting as sudden, brief paroxysms of axial hypotonia (PNKD3)." (PMID 35819138, 2022). "The limitations of genotype and phenotype assessment also hamper the understanding of KCNMA1 channelopathy disease mechanisms." (PMID 34224328, 2021). "The establishment of the KCNMA1-channelopathy consortium has truly pushed BKCa as a therapeutic target for several neuronal and other possible diseases." (PMID 32824463, 2020). "Such investigations in patient tissues may also better address the phenotypic variability in KCNMA1 channelopathy that can arise from differences in genetic backgrounds between patients." (PMID 40785052, 2025). "Although patients circumstantially report sleep disturbance and high sensitivity to sleep loss, this has not been directly addressed yet in KCNMA1 channelopathy patient clinical genotype–phenotype correlations." (PMID 37728576, 2023). "It is difficult to determine which BK channel components target which neuron or muscle loci in KCNMA1-linked channelopathy without more precise information." (PMID 36503451, 2023). "Since most variants arise de novo in a single heterozygous proband, whether ‘KCNMA1 channelopathy’ is a bona fide monogenic disorder, or results from intergenic and developmental interactions, is not well understood." (PMID 35819138, 2022). "Although N999S is the most commonly reported KCNMA1 variant, direct evidence that it caused channelopathy was lacking because it arose de novo in all known cases." (PMID 35819138, 2022). "Moreover, our data for N999S and D434G corroborate mounting evidence, both in patients and in animal models, that PNKD can be considered the most consistent symptom for KCNMA1 GOF channelopathy." (PMID 35819138, 2022).
channelopathy (continued). "The exclusive initiative by the ‘KCNMA1 channelopathy international advocacy foundation’ has brought BKCa-associated disorders to the forefront and facilitates education, treatment, and networking opportunities for KCNMA1 channelopathy patients, physicians, and researchers." (PMID 32824463, 2020). "From this study, KCNMA1 channelopathy patients harboring N999S or D434G mutations might not be expected to have a primary circadian deficit that contributes to the anecdotal reports of sleep symptoms." (PMID 37728576, 2023). "However, reviewing 37 patients with KCNMA1-linked channelopathy, paroxysmal non-kinesigenic dyskinesia (PNKD) was reported in 17 of 20 GOF patients and only 2 of 13 LOF patients." (PMID 36503451, 2023). "In the authors’ experience, PNKD episodes are frequently mistaken for seizures due to background epileptiform activity on EEG or co‐morbid epileptic seizures, which are also prevalent in KCNMA1‐linked channelopathy, despite the lack of confirmatory abnormalities on scalp EEG during the dyskinesias." (PMID 35141357, 2022). "These variants support the conclusion that KCNMA1 plays a pathogenic role in KCNMA1-linked channelopathy, although it may not represent the entire molecular picture of the disorder in all cases." (PMID 34224328, 2021). "However, Kcnma1‒/‒ mice do not overtly exhibit KCNMA1-linked channelopathy symptoms." (PMID 35819138, 2022). "However, the classic description of cataplexy involves a sudden and near-complete loss of tone with absent deep tendon reflexes, while the spells seen in KCNMA1-linked channelopathy are often accompanied by preserved tone and the presence of deep tendon reflexes." (PMID 34224328, 2021). "Gain-of-function (GOF) and loss-of-function (LOF) alterations in BK channel activity disrupt circadian behavior, but the effect of human disease-associated KCNMA1 channelopathy variants has not been studied on clock function." (PMID 37728576, 2023). "KCNMA1 LOF channelopathy has also been proposed to carry a broader set of non-overlapping features associated with a subset of de novo LOF variants, referred to as Liang-Wang syndrome." (PMID 35819138, 2022). "Taken together, SNP analysis suggests the potential involvement of KCNMA1 and the BK channel in a wide range of human diseases, and the variant associations are not delimited by the core features of KCNMA1-linked channelopathy." (PMID 34224328, 2021).
autism (15 papers, 2012 to 2025). Persistent deficits in social interaction and communication and interaction as well as a markedly restricted repertoire of activity and interest as well as repetitive patterns of behavior. "Mutations in the genes encoding the large-conductance calcium-activated potassium channel, especially KCNMA1 encoding its α-subunit, have been linked to several neurological features, including intellectual disability or autism." (PMID 35509069, 2022). "Diseases associated with KCNMA1 include autism, cerebellar atrophy, and generalized epilepsy and paroxysmal dyskinesia [MIM 609446]." (PMID 29924869, 2018). "Consistent with this idea, PMS and human KCNMA1/BK mutations are associated with several shared phenotypes including: autism, developmental delay, intellectual disability, hypotonia, seizures, and gastrointestinal defects (i.e. vomiting, constipation, or diarrhea)." (PMID 35266450, 2022). "KCNMA1 mutations have increasingly been linked to several neurological disorders, including epilepsy, cerebellar ataxia, paroxysmal movement disorders, intellectual disability (ID), or autism, underscoring the important role of BKCa channels in controlling neuronal excitability." (PMID 35509069, 2022). "Molecular and functional studies found that defects of KCNMA1 contribute to autism and mental retardation." (PMID 23264780, 2012).
prostate carcinoma (15 papers, 2010 to 2026). A carcinoma that arises from epithelial cells of the prostate gland. "KCNMA1 gene amplification was also associated with progression to late-stage, metastatic, and hormone-refractory human prostate cancer, and was associated with a high BKCa channel density in the cellular membrane in the PC-3 prostate cancer cell line." (PMID 33923707, 2021). "We previously detected genomic amplification of the BK channel encoding gene KCNMA1 in 16% of late-stage prostate cancers, identifying KCNMA1 as one of the most common amplifications in prostate cancer." (PMID 22899999, 2012). "Since amplification of KCNMA1 was restricted to gynecological and prostate cancers, we tested the association between BK-mRNA levels in cell lines originating from (a) hormone sensitive versus (b) hormone insensitive organs." (PMID 22899999, 2012). "KCNMA1 encodes the α-subunit of the large conductance, voltage and Ca2+-activated (BK) potassium channel and has been reported as a target gene of genomic amplification at 10q22 in prostate cancer." (PMID 22899999, 2012). "The large-conductance voltage- and Ca2+-activated K+ channel Slo1 (BK, KCNMA1) was found upregulated in prostate cancer cells." (PMID 34620975, 2021). "In the present study, we investigated the prevalence of the KCNMA1 amplification beyond prostate cancer." (PMID 22899999, 2012). "In comparison, proliferation of the KCNMA1-amplified prostate cancer cell line PC3 was strongly reduced by both treatments." (PMID 22899999, 2012). "The aim of this study was to investigate the prevalence of KCNMA1 amplification in cancers beyond prostate cancer, and to explore its functional and prognostic consequences." (PMID 22899999, 2012). "KCNMA1 is shown to be amplified in primary prostate cancer tumors and PC3 cell line, and siRNA knock-down implicates KCNMA1's critical role in prostate cancer development." (PMID 20830292, 2010). "Previously, we reported amplification of KCNMA1 in 16% of advanced-stage human prostate cancers." (PMID 22899999, 2012). "Large conductance, voltage- and Ca2+-activated potassium channel (KCNMA1; BK) is located at 10q22.3 and was recently found to be amplified in a proportion of castration-refractory human prostate cancers, suggesting an involvement in the progression of the disease." (PMID 22899999, 2012). "Further studies are needed to elucidate the complex interplay between sex hormones and KCNMA1 in breast- and prostate cancer that is likely to be influenced by the type of regulatory ß-subunits of the BK channel, alternative splicing, the background of ER and/or AR status, and anti-hormone therapy." (PMID 22899999, 2012). "KCNMA1 was also found amplified in 16% of the human prostate cancer." (PMID 20830292, 2010). "Large conductance calcium-activated potassium channel alpha subunit gene (KCNMA1), the only gene in its FMCR, has been shown to be gained in prostate cancer cases and overexpressed in metastatic breast cancer." (PMID 24367615, 2013).
alcohol dependence (13 papers, 2012 to 2025). Physical and psychological dependence on alcohol. "KCNMA1, the mammalian ortholog of slo-1, has been associated with alcohol dependence in humans and other alcohol-related behaviors like sensitivity in rodents." (PMID 38999947, 2024). "KCNMA1 has also been implicated in multiple substance use disorders, and alcohol dependence has been of particular interest due to ethanol’s capacity to activate the BK channel in model organisms." (PMID 34224328, 2021). "In human genetics studies, both KCNMA1 and the genes encoding β subunits of the BK channel have been associated with alcohol dependence." (PMID 25249984, 2014). "We note that KCNMA1 is known as a gene associated with alcohol dependency." (PMID 37170185, 2023). "Specifically, KCNMA1 is known as a gene associated with alcohol dependency." (PMID 36371147, 2022). "Finally, two separate GWAS studies associated the human ortholog KCNMA1 (potassium calcium-activated channel subfamily M alpha 1) with alcohol dependence." (PMID 32932795, 2020). "However, subsequent larger GWAS have also identified suggestive and significant associations with KCNMA1 and alcohol dependence, thus providing additional support for this association." (PMID 33066036, 2020). "There is also evidence from several human genetic studies implicating KCNMA1 in LR and alcohol dependence." (PMID 33066036, 2020). "When they tested their final 39-gene network, which included both KCNMA1 and KCNMB1, for association with alcohol dependence, they found significant associations in both European Americans and African Americans in the merged COGA and SAGE GWAS data sets." (PMID 25249984, 2014). "Furthermore, two recently published human GWA studies have provided preliminary evidence for a link between Kcnma1 and alcohol dependence." (PMID 22511924, 2012).
developmental delay (13 papers, 2018 to 2025). "KCNMA1 is typically associated with paroxysmal non‐kinesigenic dyskinesia, developmental delay, and seizures, with LoF being a known disease mechanism." (PMID 40533913, 2025). "In contrast, dysfunction of BK CAKCs encoded by the KCNMA1 gene, which are widely expressed in many tissues, is associated with complex combinations of disorders, including seizures, movement disorders, developmental delay and intellectual disability." (PMID 38419657, 2024). "Biallelic variant in KCNMA1 is associated with cerebellar atrophy, developmental delay and seizures (OMIM 617643)." (PMID 37288276, 2023). "Of note, the malnutrition and developmental delay caused by the weak grip of BK KO mice are reminiscent of the developmental delay found in the patient with the KCNMA1-LOF (E155Q) variant." (PMID 35095492, 2021). "KCNMA1-linked channelopathy is an emerging neurological disorder characterized by heterogeneous and overlapping combinations of movement disorder, seizure, developmental delay, and intellectual disability." (PMID 34224328, 2021). "Recent research has established homozygous KCNMA1 mutations accountable for the phenotype of cerebellar atrophy, developmental delay, and seizures." (PMID 29545233, 2018). "A recent study established a correlation of the homozygous KCNMA1 mutation with cerebellar ataxia, developmental delay, and seizures." (PMID 29545233, 2018). "KCNMA1-linked channelopathy is a recently characterized neuromuscular disorder essentially defined by the presence of a mutation in the KCNMA1 gene, associated with various combinations of movement disorders, seizures, developmental delay, and intellectual disability." (PMID 34224328, 2021). "Heterozygous pathogenic variants in KCNMA1 cause Liang-Wang syndrome (OMIM 618729), a severe neurological disorder that may include severe global developmental delay, craniofacial dysmorphism and visceral and connective tissue abnormalities." (PMID 37288276, 2023). "Notably, patients with both GOF and LOF KCNMA1 showed developmental delay and intellectual disability; a subset of neurodevelopmental symptoms has only been described in patients with LOF KCNMA1." (PMID 36503451, 2023).